IL6 (interleukin 6)
Diseases named in the same sentence as IL6 in open-access papers (continued):
Sharing a sentence is not in itself a finding about the gene and the disease.
depression (continued). "Some studies have indicated that higher blood levels of pro-inflammatory cytokines TNF-α and IL-6 in drug-free patients with depression." (PMID 27931233, 2016). "IL-6 is a pleiotropic inflammatory cytokine secreted by activated glia in the Central Nervous System (CNS) and is involved in mood disorders such as depression, also in aging process and the pathogenesis of neurodegenerative diseases such as AD." (PMID 27803663, 2016). "Consistent with our results, alterations in inflammatory markers, including an increase in serum IL6, have been observed in children and adolescents with major depressive disorder." (PMID 27489945, 2016). "Kiecolt-Glaser and Glaser presented an argument that psychological stress and depression increase IL-6, a marker of inflammation, and decrease cellular and humoral immunity." (PMID 28030615, 2016). "Apart from the relatively new findings about IL-6, stress and depression, IL-6 is a confirmed modulator of pain processing." (PMID 26821321, 2016). "The co-occurrence of these usually painful medical conditions and depression has been proposed to have a common neuroinflammatory aetiological background with the involvement of IL-6 and other cytokines." (PMID 26821321, 2016). "IL-6 was also elevated in subjects exposed to various depression-related stressful circumstances like childhood abuse, low socioeconomic status, negative social interactions, or parental loss." (PMID 26821321, 2016). "This study indicates a significant correlation between serum IL-6 level and depression in patients undergoing HSCT." (PMID 25922648, 2015). "Among continuous variables, patients with depression had significantly higher concentrations of IL-6 and IL-6 to IL-10 ratios (P<0.001)." (PMID 25922648, 2015). "Oppositely, mice with targeted deletion of IL-6 or TNFα receptors display resistance to depression-like behaviors." (PMID 25947540, 2015). "The multivariate logistic regression test after adjusting for body mass index, age, sex, education level, marital status showed there is a direct effect of IL-6 with depression (P<0.001, odds ratio [OR] = 1.05; 95% confidence interval [CI] = 1.02–1.09)." (PMID 25922648, 2015). "This evidence includes consistent findings of increased serum levels in patients with depression of certain pro-inflammatory cytokines, particularly tumor necrosis factor-α (TNFα) and interleukin-6 (IL-6)." (PMID 25947540, 2015). "Of the inflammatory markers studied in the present study, CRP, IL–6 and TNF- α have been previously shown to have an association with depression / anxiety." (PMID 26445118, 2015). "STAT3 IL6-dependently associated with the SERT promoter and inhibition of STAT3 blocked the effect of IL6 in-vitro and modulated depression-like behavior in-vivo." (PMID 25760924, 2015). "There are also evidences from large-study that low-grade chronic inflammatory markers, such as C-reactive protein and interleukin-6 are connected with cognitive symptoms of depression." (PMID 25793613, 2015). "IL-6, TNFα, IL-1β and their soluble receptors have been found to be upregulated in patients with major depression." (PMID 26793110, 2015). "These consistent clinical findings indicate that TNF-α and IL-6 are putative biomarkers of depressive episodes and treatment response." (PMID 25793613, 2015). "Administration of IFN-alpha induces a number of other inflammatory cytokines in the periphery and central nervous system (CNS) that are elevated in depression, including interleukin-6 and tumor necrosis factor." (PMID 25638816, 2015). "C-reactive protein (CRP), interleukin–6 (IL–6), and tumor necrosis factor alpha (TNF-α) have previously been shown to associate with LUTS, depression and anxiety, while myeloperoxidase (MPO) has also been linked to the development of depression." (PMID 26445118, 2015). "Our results showed that there is a relationship between increased IL-6-to-IL-10 ratios with depression in patients undergoing HSCT (P<0.001)." (PMID 25922648, 2015).
depression (continued). "In this study we evaluate relation between depression and IL-6 and IL-10 in patients undergoing hematopoietic stem cell transplantation (HSCT)." (PMID 25922648, 2015). "Elevations in proinflammatory cytokines like prostaglandin E2 (PGE2), C-reactive protein (CRP), TNF-α, IL-1β, IL-2, and IL-6 have been reported in major depressive disorder and, at times, have shown a dose-response with severity of depression." (PMID 26550011, 2015). "Majority (67.6%) of our Rheumatoid Arthritis patients had active disease and would have high inflammatory cytokines like TNF and IL-6 which is also contributing to depression." (PMID 26101498, 2015). "Especially interleukin-6 has been correlated to MM progression as well as to cancer-related depression and fatigue 35,36." (PMID 25155101, 2015). "A recent longitudinal study conducted in England revealed that children with elevated serum IL-6 and CRP levels were more at risk to develop depression and psychosis later in life." (PMID 26217190, 2015). "Uncontrolled, elevated inflammatory markers (e.g. interleukin-6 [IL-6], tumor necrosis factor-alpha) can occur via a dysfunctional hypothalamic pituitary adrenal axis (e.g. during chronic stress, depression)." (PMID 26384322, 2015). "Conversely, hippocampal tissue of IL6-KO mice contained elevated levels of SERT and IL6-KO mice displayed a reduction in depression-like behavior and blunted response to acute antidepressant treatment." (PMID 25760924, 2015). "Patients with major depressive disorders have higher levels of proinflammatory cytokines, such as interleukin-6, interleukin-1, and tumor necrosis factor-alpha, than the general population." (PMID 26770976, 2015). "SNPs in genes for IL-1, IL-6, tumor necrosis factor alpha (TNFα), cyclooxygenase 2 (COX2), superoxide dismutase (SOD), and catalase is associated with depression." (PMID 26078821, 2015). "Elevated concentrations of IL-6 have been associated with symptoms of insomnia, PTSD, and depression." (PMID 25983695, 2015). "Childhood inflammation (IL-6) has been recently demonstrated to even precede the diagnosis of depression and psychosis in a prospectively followed general population cohort." (PMID 25790282, 2015). "The interaction effect of chronic interpersonal stress and IL6 genotype on depression severity held under these conditions: b = -.48 [95% CI: -0.86 to -0.11], Δ R2 = 0.01, Δ F = 6.36, p = .01." (PMID 25596176, 2015). "Elevated pro-inflammatory cytokines, such as IL-6 and TNF-α, along with CRP have been found in depressive patients; however, the association between CRP and depression is controversial." (PMID 27429271, 2014). "A more recent meta-analysis by Dowlati and colleagues has supported the role of pro-inflammatory markers in depression, in particular IL-6 and tumor necrosis factor (TNF)-α." (PMID 24239712, 2014). "Patients suffering from depression exhibit increased levels of the proinflammatory cytokine interleukin-6 (IL-6) while at rest and exhibit greater social stress-induced IL-6 levels, which are normalized following antidepressant therapy." (PMID 25206349, 2014). "Depression has been characterised as an increased inflammatory status (inflammaging) including elevated levels of pro-inflammatory cytokines, including IL6, TNFα and IL1β." (PMID 25628751, 2014). "Plasma concentrations of the proinflammatory cytokines IL-1 and IL-6 are increased in patients with depression and antidepressant medication reduces the concentrations of cytokines such as IL-1β." (PMID 25593715, 2014). "It is thought that the acute-phase response in patients with major depression is related to increased production of pro-inflammatory cytokines, such as IL-1 and IL-6." (PMID 24894416, 2014). "Similar associations between depression and C-reactive protein (CRP), IL-6, and, to a lesser extent, IL-1 have been found in patients with cardiac disease or cancer." (PMID 24723864, 2014).
depression (continued). "Abbasi showed that antidepressant celecoxib can reduce HDRS scores as well as IL-6 concentration in patients with major depressive disorders." (PMID 24795767, 2014). "Numerous studies indicate that proinflammatory cytokines (IL-1β, IL-6, TNF-α, IFN-α (interferon α), IFN-γ, soluble receptor for IL-6, antagonist of the receptor for IL-1) are crucial factors in etiopathogenesis of depression." (PMID 25530618, 2014). "Plasma concentrations of proinflammatory cytokines IL-1 and IL-6 increase in patients with depression; in patients taking antidepressant medications, reduction of plasma IL-1β appears to be associated with the treatment." (PMID 25237578, 2014). "A second limitation of this study is the lack of a comparison between suPAR measurements and other components of the fibrinolytic system or other inflammatory markers previously shown to be associated with depression, such as CRP or IL-6." (PMID 25329298, 2014). "Patients undergoing cytokine therapy often develop symptoms of depression and elevated levels of cytokines (including IL-6 and IL-1β) are found in both blood and CSF from depressed patients." (PMID 25285951, 2014). "Several studies reported increased levels of proinflammatory cytokines, for example, tumor necrosis factor-alpha (TNF-α) and interleukin-6 (IL-6) in depressive disorders." (PMID 25587342, 2014). "Experimental and clinical evidence has suggested that depression and depressive symptoms are accompanied by elevated levels of pro-inflammatory cytokines, including IL6, TNFα and IL1β." (PMID 23876747, 2013). "We considered earlier the evidence that there is a form of inflammation-associated depression, accompanied by raised CRP and IL-6, that is common in rich urban societies, but probably rare in low-income countries." (PMID 24481186, 2013). "Elevated IL-6 has been linked with reduced hippocampal volume and cognitive decline in the elderly while studies of depression have implicated IL-1β, TNF-α and IL-6." (PMID 23840908, 2013). "Amongst others, interleukin-6 (IL-6) became most often used marker to link depression and inflammation in patients with CKD, ESRD and after kidney transplantation." (PMID 22972567, 2013). "Elevated IL-6 has served as a consistent biomarker of depression and IL-10 is proposed to influence depressive behavior through its ability to counterbalance pro-inflammatory cytokine expression." (PMID 23520517, 2013). "In the CSF, high levels of IL-6 in patients with depression vs controls were reported with highest elevations in depressed patients with a recent violent suicide attempt." (PMID 23951008, 2013). "While elevated IL-6 is itself reported as a biomarker of depression, animal studies show the behavioral effects of IL-6 alone to be inconsistent." (PMID 23520517, 2013). "In a clinical study, patients with depressive episodes demonstrated an increase in IL-6 levels, whereas patients with maniac episodes showed an increase in IL-2, IL-4, and IL-6 levels." (PMID 23497121, 2013). "In depressed patients, many studies have reported an association between elevated levels of peripheral inflammatory markers (for example, plasma IL-6 and C-reactive protein) and symptoms of major depression." (PMID 23866724, 2013). "Detrimental effects on the other hand, are described between high concentrations of IL-6, reduced hippocampal volumes and major depressive disorders and in chronic systemic inflammatory conditions with increased risk of stroke." (PMID 24133408, 2013). "Nonetheless, when put in the context of human studies which measure elevated peripheral IL-6 in depression, cognitive decline and CNS disease the current results are not consistent with direct CNS inflammatory effects of systemic IL-6." (PMID 23840908, 2013). "Mounting studies reveal that both IL-1β and IL-6 are important in the etiology and pathophysiology of depression." (PMID 23596475, 2013).
depression (continued). "Recent literature describes concurrent increases in IL-6 and decreases in IL-10 in individuals suffering from major depression." (PMID 23520517, 2013). "For example, BC− patients were found to have a positive correlation with IL-6 and level of depression (P < 0.01)." (PMID 22830048, 2012). "The recent finding of pathologically high levels of cytokines in the brain (IL-6) of suicide attempters links somatic symptoms with suicidal behavior and severity of depression." (PMID 22839681, 2012). "There is an increasing body of evidence that point at depression as an inflammatory disorder prompted by deregulated levels of pro-inflammatory cytokines, such interleukin-1β, IL-6, tumor necrosis factor-α, IFN-γ and IFN-γ-induced protein 10 (IP-10)." (PMID 22701688, 2012). "Metabolic syndrome, a state of increased weight around the waist, is associated with high levels of IL-6 and CRP and is also a risk factor for depression." (PMID 22912626, 2012). "The aim of this study was to examine serum levels of the proinflammatory cytokines interleukin 6 (IL-6) and tumor necrosis factor α (TNFα), and the anti-inflammatory cytokine IL-10, in perimenopausal women suffering from depression." (PMID 22490187, 2012). "Kubota and colleagues found elevated TNF-α and IL-6 in people with HF, while other studies reported similar findings in patients with depression and HF." (PMID 22919538, 2012). "He found increased plasma levels of IL-6 in the subgroup of women with depression and hot flashes when compared to women with hot flashes without depression and to control subjects." (PMID 22490187, 2012). "Recent meta-analyses and recent publications have confirmed increased levels of PICs in human depression particularly IL-6, TNFα, and IL-1, and CMI activation, evidenced by higher levels of neopterin and soluble IL-2 receptors (sIL-2Rs)." (PMID 22747645, 2012). "Proinflammatory cytokines, such as interleukin 6 (IL-6) and tumor necrosis factor α (TNFα) have been considered as key neuromodulators of behavioral, neuroendocrine and neurochemical features of depressive disorders." (PMID 22490187, 2012). "After controlling for lifetime duration of depression, the relationships between the oxidative stress ratio and IL-6 concentrations and telomere length remained significant (F = 4.91, p<0.02, and F = 3.46, p<0.05, respectively)." (PMID 21448457, 2011). "Immune dysfunction, including monocytosis and increased blood levels of interleukin-1, interleukin-6 and tumour necrosis factor α has been observed during acute episodes of major depression." (PMID 21831269, 2011). "A cluster of cytokines including interleukin-1 beta (IL-1β), IL-2, IL-6, interferon-gamma, and tumor necrosis factor alpha (TNFα) have been reported to correlate with depression symptoms." (PMID 21864357, 2011). "Leukocyte telomere length was compared between 18 unmedicated MDD subjects and 17 controls and was correlated with lifetime depression chronicity and peripheral markers of oxidation (F2-isoprostane/Vitamin C ratio) and inflammation (IL-6)." (PMID 21448457, 2011). "Concerning the immunological mechanisms, certain pro-inflammatory cytokines, mainly IL-6, IL-1β and TNFα, have been recently pointed out as pivotal molecules for depression-related behaviors following infection." (PMID 21194425, 2010). "Functional polymorphisms in the promoter of the IL6 gene and in the promoter region of the serotonin transporter (5-HTT) gene have been shown to be associated with a lower risk of symptoms of depression during IFNα treatment." (PMID 27713294, 2010). "Elevated circulating IL-6, altered striatal dopaminergic neurotransmission, and psychomotor slowing are also reported in people with clinical depression." (PMID 18242584, 2008). "All these data suggest that the general assertion regarding IL-6, depression and cancer needs great caution." (PMID 17288583, 2007).
depression (continued). "The proinflammatory cytokines that researchers identified most consistently as being elevated in depression are interleukin-1β (IL-1β), interleukin-6 (IL-6), tumor necrosis factor-α (TNF-α), and more recently, interferon-γ (IFN-γ)." (PMID 17397549, 2007). "The findings ofpresent study are in line with reports indicating an increase inthe production or secretion of IL-6 and IL-l in subjects withmajor depression." (PMID 17497035, 2007). "In a study of older adults, the combination of depression and higher omega-6: omega-3 ratios dramatically increased levels of proinflammatory cytokines (IL-6 & TNF-α) beyond the individual contribution of either variable alone." (PMID 17397549, 2007). "Statistically significant finding of cytokines in our research, as well as presence of cytokines IL-2 and IL-6 which are analyzed in relation to depression, confirms the existence of relationship between depression and BMS." (PMID 16864905, 2006). "In our model, MGO not only elevated depression-related markers such as GR and cortisol but also increased free MGO and pro-inflammatory cytokines (IL-1β, IL-6, TNF-α), implicating activation of inflammatory pathways that underlie psychoneuroimmunity-related depression." (PMID 41355970, 2026). "Moreover, a meta-analysis of 20,791 children and adolescents associated concurrent depression with CRP and IL-6, while depression proved a significant predictor of IL-6." (PMID 41515266, 2026). "Moreover, high levels of IL-6 were associated with a rapid progression of depressive symptoms in patients, and TNF-α was also linked to worsening depression." (PMID 41601490, 2026). "Interestingly, longitudinal data associate higher inflammatory marker concentrations, such as IL-6, at the age of 9 years in females with worse depression symptoms compared to males." (PMID 41515266, 2026). "Elevated levels of cytokines such as TNF-α, IL-1β, and IL-6 may exacerbate neuroinflammatory responses, with their concentrations positively correlating with the severity of depression." (PMID 40427467, 2025). "This evidence supports the idea that cancer patients experiencing fatigue, anxiety, and depression may have elevated levels of circulating inflammation markers, such as interleukin‐6 (IL‐6) and C‐reactive protein (CRP)." (PMID 40387308, 2025). "Taken together, these data demonstrate that the IL-6/STAT3 signaling pathway plays an important role in depression or depression-like behavious, and targeting this pathway may provide a novel therapeutic approach for the treatment of this disorder." (PMID 40115872, 2025). "Recent findings from the COVID pandemic further bolster the connection between inflammation (in this case acute inflammation triggering a storm of pro-inflammatory cytokines such as interleukin-6 (IL-6), tumor necrosis factor-alphaTNF-α), and interleukin-1 betaIL-1β)) and depression." (PMID 41442021, 2025). "Additionally, it was reported that interleukin-1α, IFN-γ, interleukin-6, interleukin-8, interleukin-12, and other pro-inflammatory cytokines were reduced when SSRIs were used for the treatment of depression." (PMID 40161243, 2025). "Obesity-induced inflammation significantly heightens oxidative stress by increasing adipokine secretion—such as IL-6, IL-1, and tumor necrosis factor-alpha—while simultaneously impairing insulin regulation, thus elevating risks for type 2 diabetes and depression." (PMID 40426956, 2025). "Consequently, the IL‐6/IL‐6R pathway has emerged as a promising target for the treatment of depression." (PMID 39888279, 2025). "In patients with depression, a higher concentration of IL-6 in peripheral blood is observed." (PMID 40141110, 2025). "Increased concentrations of biomarkers of low-grade inflammation such as C-reactive protein (CRP; >3 mg/L) have been identified, together with elevated levels of interleukin (IL)-6 and other inflammatory cytokines in blood and cerebrospinal fluid of patients with depression." (PMID 38545720, 2025).